TRMT10C (tRNA methyltransferase 10C, mitochondrial RNase P subunit)
Description:
Mitochondrial tRNA N(1)-methyltransferase involved in mitochondrial tRNA maturation. Component of mitochondrial ribonuclease P, a complex composed of TRMT10C/MRPP1, HSD17B10/MRPP2 and PRORP/MRPP3, which cleaves tRNA molecules in their 5'-ends. Together with HSD17B10/MRPP2, forms a subcomplex of the mitochondrial ribonuclease P, named MRPP1-MRPP2 subcomplex, which displays functions that are independent of the ribonuclease P activity. The MRPP1-MRPP2 subcomplex catalyzes the formation of N(1)-methylguanine and N(1)-methyladenine at position 9 (m1G9 and m1A9, respectively) in tRNAs; TRMT10C/MRPP1 acting as the catalytic N(1)-methyltransferase subunit. The MRPP1-MRPP2 subcomplex also acts as a tRNA maturation platform: following 5'-end cleavage by the mitochondrial ribonuclease P complex, the MRPP1-MRPP2 subcomplex enhances the efficiency of 3'-processing catalyzed by ELAC2, retains the tRNA product after ELAC2 processing and presents the nascent tRNA to the mitochondrial CCA tRNA nucleotidyltransferase TRNT1 enzyme. In addition to tRNA N(1)-methyltransferase activity, TRMT10C/MRPP1 also acts as a mRNA N(1)-methyltransferase by mediating methylation of adenosine residues at the N(1) position of MT-ND5 mRNA. Associates with mitochondrial DNA complexes at the nucleoids to initiate RNA processing and ribosome assembly.
Synonyms: MRPP1; RG9MTD1; FLJ20432; COXPD30; HNYA
Tractability: Small molecule: a structure with a bound ligand is known. PROTAC: ubiquitination databases record sites on it; its protein half-life has been measured.
Gene: Protein-coding gene on chromosome 3 (101,561,868 to 101,566,446, forward strand). Ensembl gene ENSG00000174173.
Subcellular location: Mitochondrion matrix, mitochondrion nucleoid
Subcellular location (Human Protein Atlas): Mitochondria; Nucleoplasm
Pathways (Reactome):
Metabolism of RNA: rRNA processing in the mitochondrion; tRNA modification in the mitochondrion; tRNA processing in the mitochondrion
Gene Ontology:
Molecular function: identical protein binding; protein binding; RNA binding; tRNA (adenine(9)-N1)-methyltransferase activity; tRNA (guanosine(9)-N1)-methyltransferase activity; tRNA binding
Biological process: mitochondrial RNA 5'-end processing; mitochondrial tRNA 3'-end processing; mitochondrial tRNA 5'-end processing; mitochondrial tRNA methylation; mitochondrial tRNA processing; mRNA processing; tRNA 3'-end processing; tRNA 3'-terminal CCA addition; tRNA processing
Cellular component: catalytic complex; endoribonuclease complex; mitochondrial matrix; mitochondrial nucleoid; mitochondrial ribonuclease P complex; mitochondrion; tRNA methyltransferase complex; nucleoplasm; nucleus
Genetic constraint (gnomAD): Loss-of-function variants: 15 observed, 30.39 expected, observed/expected ratio (o/e) 0.49, 90% interval 0.33 to 0.76. The upper end of that interval is the gene's LOEUF score, 0.76, which puts it in group 3 of 6, group 1 being the genes least tolerant of losing a copy. Missense variants: 438 observed, 484.86 expected, observed/expected ratio (o/e) 0.9, 90% interval 0.83 to 0.98. Synonymous variants: 143 observed, 164.77 expected, observed/expected ratio (o/e) 0.87, 90% interval 0.76 to 1.
Gene-disease validity (ClinGen):
ClinGen rates the evidence that TRMT10C causes each of these diseases.
mitochondrial disease (autosomal recessive): Moderate.
Homologues: Orthologues: chimpanzee TRMT10C (99% identical), macaque TRMT10C (90% identical), pig TRMT10C (81% identical), rabbit TRMT10C (78% identical), mouse Trmt10c (76% identical), dog TRMT10C (75% identical), rat Trmt10c (74% identical), tropical clawed frog trmt10c (46% identical), zebrafish trmt10c (42% identical), Drosophila melanogaster rswl (25% identical), Caenorhabditis elegans trmt-10C.1 (20% identical), Caenorhabditis elegans trmt-10C.2 (17% identical). Paralogues in human: TRMT10B (17% identical), TRMT10A (17% identical).
Diseases named in the same sentence as TRMT10C in open-access papers:
TRMT10C is named in the same sentence as 17 diseases in open-access papers, as found by Europe PMC text mining. Sharing a sentence is not in itself a finding about the gene and the disease. The quoted sentences say what the papers report.
cervical cancer (2 papers, 2024). A primary or metastatic malignant neoplasm involving the cervix. "In addition, TRMT10C is highly expressed in cervical cancer and ovarian cancer tissues, promoting the proliferation, colony formation and migration of ovarian cancer and cervical cancer cells, which may be related to the regulation of C-MYC-related pathways." (PMID 38343637, 2024).
glioma (2 papers, 2021 to 2022). A benign or malignant brain and spinal cord tumor that arises from glial cells (astrocytes, oligodendrocytes, ependymal cells). "The differential analysis showed that ALKBH1, TRMT6, TRMT10C, YTHDF1, and YTHDF2 were significantly overexpressed in high-grade gliomas." (PMID 34631793, 2021). "We found that ALKBH1, TRMT6, TRMT10C, YTHDF1, and YTHDF2 were significantly overexpressed in high-grade gliomas and the expression of TRMT6 and YTHDF2 was higher in IDH wild-type patients." (PMID 34631793, 2021).
deafness (1 paper, 2016). An inherited or acquired condition characterized by the complete loss of the ability to hear from one or both ears. "Using whole-exome sequencing, we identified mutations in TRMT10C (encoding the mitochondrial RNase P protein 1 [MRPP1]) in two unrelated individuals who presented at birth with lactic acidosis, hypotonia, feeding difficulties, and deafness." (PMID 27132592, 2016).
gynecological cancers (1 paper, 2024). "To date, only one publication has suggested that TRMT10C is significantly upregulated in CESC, OV, and UCEC and is associated with an unfavorable prognosis in patients with gynecological cancers." (PMID 39247598, 2024).
hepatoblastoma (1 paper, 2024). Hepatoblastoma (HB) is a malignant hepatic tumor and is the most common pediatric liver cancer. "Our results suggest that the role of TRMT10C in the tumorigenesis of hepatoblastoma should be explored." (PMID 39247598, 2024).
hepatocellular carcinoma (1 paper, 2025). A malignant tumor that arises from hepatocytes. "The elevated expression of m1A methyltransferases (TRMT10C, TRMT6) and ribosomal RNA processing protein 8 (RRP8), along with m5C reader YBX1, demonstrate a significant association with unfavorable prognosis in hepatocellular carcinoma." (PMID 40699703, 2025).
tumor (6 papers, 2021 to 2023). "The staining intensity of TRMT61B, TRMT10C and ALKBH1 in tumor tissue is higher than that in normal kidney tissue." (PMID 37542141, 2023). "Among the regulatory genes, ALKBH1 and ALKBH3, which are methylation erasers, were upregulated and TRMT10C, TRMT6, TRMT61B, YTHDF2, and YTHDF3 were downregulated in tumor samples in comparison to normal tissues." (PMID 37679761, 2023). "In terms of mRNA levels, TRMT6, TRMT61A, TRMT61B, TRMT10C, YTHDF1 and YTHDF2 YTHDF3 were overexpressed in tumor sample." (PMID 34777359, 2021).
cancer (5 papers, 2022 to 2024). A tumor composed of atypical neoplastic, often pleomorphic cells that invade other tissues. "Moreover, tRNA methyltransferase 10C (TRMT10C), catalyzing the mitochondrial ND5 mRNA at N1-methyladenosine (m1A) site, promotes cancer cell metabolism by reducing the mitochondrial ribonuclease P protein 1 (MRPP1) in mitochondria and inducing protein instability and mt-tRNA processing." (PMID 36010594, 2022). "Further analyses revealed that RAB42 overexpression is positively correlated with writer genes TRMT10C, TRMT61B and reader gene DNMT3B in most cancers." (PMID 39101146, 2024). "The other hub genes (e.g., YBX1, OLA1, TRMT10C, and KIF20A) also play a key role in the development and prognosis of the pan-cancer section." (PMID 35720008, 2022).
mitochondrial disease (4 papers, 2016 to 2024). "We show that N6AMT1 is required for the translation of PRORP and TRMT10C, two subunits of the mitochondrial RNAse P which are central for mitochondrial gene expression, and which are also implicated in mitochondrial disease." (PMID 39503847, 2024).
infection (1 paper, 2021). The state of being infected such as from the introduction of a foreign agent such as serum, vaccine, antigenic substance or organism. "Depletion of TNFAIP3, ATF3, TAF7, and TRMT10C mildly to moderately reduced VEEV-TrD infection." (PMID 33788849, 2021).
TRMT10C also shares sentences with these, for which no sentence is quoted: diabetes (1 paper); diabetic retinopathy (1); digestive system neoplasm (1); Hyperglycemia (1); lactic acidosis (1); ovarian carcinoma (1); retinopathy (1).